IL33 (interleukin 33)
Diseases named in the same sentence as IL33 in open-access papers (continued):
Sharing a sentence is not in itself a finding about the gene and the disease.
asthma (continued). "In the context of asthma, rhinoviral infection may also exacerbate airway remodeling through induction of cup cell metaplasia, increased mucus production and activation of signaling pathways associated with type 2 responses (e.g., IL-33, TSLP)." (PMID 40746413, 2025). "Similarly, in the case of IL-33, several SNPs have been described that may be associated with the occurrence of asthma." (PMID 38731070, 2024). "We sought to assess whether the upper airway epithelium of patients with asthma may be an alternative source for the measurement of intracellular alarmin cytokines (TSLP, IL-25, and IL-33) in asthma and whether their expression is altered in association with asthma severity." (PMID 38999286, 2024). "Moreover, as shown in our related previous study, per-nasal delivery of IL-33 alone to the airway of wild-type mice was apparently sufficient to induce all of the pathophysiological processes in the airways associated with asthma, including AHR, predominantly eosinophilic, goblet cell hyperplasia." (PMID 35524325, 2022). "Finally, our rare variant analyses replicated a previous association in IL33 and suggest some asthma common variant loci may contain additional rare variant support." (PMID 35368043, 2022). "Increased levels of IL-33 have been found in asthma patients as well as in lesions of epidermal keratinocytes from patients with atopic dermatitis, and genomewide analyses demonstrate an association of gene loci for IL-33 or ST2 with increased risk of asthma or atopic dermatitis." (PMID 33615121, 2021). "Furthermore, the control of mucus, including the target of IL-33 and leptin, may be a therapeutic strategy for obesity-associated asthma." (PMID 34074279, 2021). "Therefore, we speculate that ICS can effectively control asthma with rs1420101 and rs4142132 mutations, through inhibiting the expression of upstream IL33." (PMID 34977013, 2021). "Moreover, it was shown that, in AEC, a haplotype within promoter IL33 might interact with DNA methylation to modulate asthma risk." (PMID 31731604, 2019). "Importantly, the effect of IL-33 on the skewing of T cell responses may play a major role in predisposing to virus-induced asthma through the differentiation of pathogenic TH2 cells over anti-viral T cells." (PMID 30949175, 2019). "Moreover, IL-33 polymorphisms influence the susceptibility to asthma." (PMID 29987222, 2018). "Similarly, IL-33 has also been associated with asthma and the TH2 response." (PMID 27378934, 2016). "Interleukin-33 (IL-33), a novel member of the IL-1 family, has recently been implicated in several inflammatory and autoimmune diseases, including atherosclerosis, sepsis, asthma, allergy, Crohn's disease, ankylosing spondylitis, arthritis, and systemic lupus erythematosus." (PMID 26557152, 2015). "Furthermore, IL-33 is increased in human asthmatics, and recent genome-wide association studies have identified the genes encoding for IL-33 and its receptor as susceptibility loci for asthma." (PMID 24453940, 2014). "Within the process of asthma pathogenesis, the IL-33/ST2 axis is known to drive mast cell activation, resulting in the release of pro-allergic cytokines and chemokines that exacerbate airway hyperresponsiveness 13,58-59." (PMID 41362726, 2026). "Taken together, these findings suggest that during virus-induced asthma exacerbations, viral infection induces epithelial alarmins—particularly IL-33—which act upstream to trigger Th2 cytokine release." (PMID 41576028, 2026). "Of the asthma-associated loci, 26/87 were GWS associated with CRSwNP, including three (5q22.1, 6p21, and 9p24.1, near genes TSLP, HLA, and IL33, respectively) associated with CRSsNP as well." (PMID 41213931, 2025). "IL-33, through interaction with its receptor ST12, has been associated with Th2-mediated immune responses in patients with asthma and increased levels of this alarmin have been detected in lung epithelial cells and serum of patients with asthma." (PMID 41246133, 2025).
asthma (continued). "IL-33 also increases collagen and fibronectin production in fibroblasts, contributing to airway remodeling in asthma." (PMID 41169790, 2025). "Clearly, IL-33 is involved in many asthma pathogenesis pathways, and its secretion leads to an increase in inflammation, which is responsible for the onset and worsening of the condition." (PMID 40723867, 2025). "IL-33 acts as an alarmin in various diseases, including inflammatory bowel disease, asthma, and atopic dermatitis (AD)." (PMID 40230853, 2025). "The genes encoding IL-33, ST-2, and IL1R1 are among the few genes that have been shown to be associated with asthma." (PMID 39962262, 2025). "Itepekimab (anti-IL-33) is a monoclonal antibody that is administered subcutaneously at a dose of 300 mg every 2 weeks, with proved benefits for asthma control, quality of life, and lung function." (PMID 40364184, 2025). "According to genome-wide association studies, the genes encoding these genes (IL33 and IL1RL1) are associated with asthma susceptibility." (PMID 41087719, 2025). "Viral infections, another well-known trigger of asthma, have also been shown to increase the release of IL-25, IL-33 and IL-1β from epithelial cells." (PMID 39962262, 2025). "Tozorakimab is another biologic that blocks IL-33 and that was shown to improve lung function and reduce blood eosinophils and FeNO in patients with moderate-to-severe asthma in a 16-week phase 2 trial." (PMID 40863432, 2025). "Large-scale genome-wide association studies (GWAS) have identified over 150 independent loci associated with asthma and 10 loci with nasal polyps (e.g. HLA-DQA1 and IL33), respectively." (PMID 40098143, 2025). "IL-33 has also been reported to potentially contribute to various lung diseases, including pulmonary fibrosis, asthma, and chronic obstructive pulmonary disease." (PMID 40100295, 2025). "Thymic stromal lymphopoietin (TSLP), IL-33, and IL-25 are epithelial-derived proinflammatory alarmin cytokines that drive inflammatory airway diseases such as asthma and chronic obstructive pulmonary disease (COPD)." (PMID 41409758, 2025). "Compared with healthy controls, asthma patients exhibit a substantial increase in IL-1β and IL-33 to IL-37 expression/production ratio." (PMID 41293155, 2025). "Concerning other investigational therapies that act at the alarmin level, ipetekimab is a monoclonal antibody directed at the alarmin IL-33 that is being investigated in type 2 inflammatory diseases, including moderate-to-severe asthma." (PMID 41473842, 2025). "In genetic association studies, multiple scattered genetic signals in the gene locus of IL33 independently promote asthma sensitivity." (PMID 39925809, 2025). "Studies have demonstrated a distinct connection between elevated levels of IL-33 and an allergic type of asthma." (PMID 40723867, 2025). "Consistent with constitutive IL-33 expression and release by dying cells, elevated IL-33 levels can be detected in a wide range of human diseases, including asthma, atopic dermatitis, ulcerative colitis, allergic rhinitis, and rheumatoid arthritis." (PMID 41409758, 2025). "Other biologics that act at the alarmin level are under study for asthma (e.g., anti-IL-33: etokimab, itepekimab; anti-IL-33R: astegolimab, melrilimab), but there are no clinical trial in CRS to date." (PMID 41473842, 2025). "IL-33-activated ILC2s are known to contribute to virus-induced bronchial hyperreactivity and allergic asthma." (PMID 39962262, 2025). "In asthma, epithelial exposure to allergens (dust mite proteases and pollen) induces IL‐33/TSLP, driving ILC2‐mediated IL‐13 production that increases airway epithelial permeability and goblet cell metaplasia." (PMID 40679787, 2025). "For instance, in a randomized Phase 2 trial involving 296 patients, itepekimab demonstrated improvements in condition and quality of life for severe asthma patients by blocking IL-33 expression compared to placebo." (PMID 39925809, 2025).
asthma (continued). "In human airway epithelial cells, AS of the IL-33 transcript with deletion of exons 3 and 4 (Δ exon 3,4) activates basophils and mast cells to drive type 2 inflammation in chronic stable asthma." (PMID 40563429, 2025). "IL-33 is a key driver of type 2 inflammation and implicated in pathology of chronic obstructive pulmonary disease (COPD) and asthma." (PMID 40553562, 2025). "The efficiency targeting IL-33 (itepekimab) and its receptor (astegolimab) for asthma have been confirmed in clinical trials, while they are failed to reach statistical significance in AD except etokimab (a humanized anti-IL-33 monoclonal antibody)." (PMID 40236701, 2025). "In asthma, IL‐33 stimulates type 2 gene expression in mast cells, resulting in sustained type 2 inflammation, which is associated with severe asthma." (PMID 40131162, 2025). "Itepekimab, an anti-IL-33 monoclonal antibody, has been compared with dupilumab in moderate-to-severe asthma." (PMID 40004611, 2025). "Like tezepelumab, other biologic therapies targeting the alarmin pathway via anti-IL-33 activity show promise for patients with T2-low asthma, but more research in phase 3 trials is needed before regulatory approval." (PMID 40863432, 2025). "Specifically, in a murine asthma model study, IL-33 induced angiogenesis and vascular permeability, while TSLP contributed to the release of VEGF-A from human lung macrophage." (PMID 40022191, 2025). "BL IL‐33 levels were equal in all groups, but within the asthma group, TSLP levels were higher in females compared to males (p < 0.0001)." (PMID 40022441, 2025). "Astegolimab, a full human IgG2 mAb targeting ST2, inhibited IL-33 signaling in a Phase 2b trial (NCT02918019) for severe asthma patients." (PMID 39925809, 2025). "Innate type 2 lymphoid cells (ILC2), which are regulated by epithelial-derived inflammatory mediators such as IL25 and IL33, also contribute to asthma-related inflammation." (PMID 40598285, 2025). "Our results align with those of previous studies that have identified IL-33 as a critical factor in chronic allergic inflammation, including asthma and AD, where it activates innate immune cells to amplify inflammation." (PMID 40715049, 2025). "In T2-high asthma, goblet cell metaplasia and epigenetic activation of alarmin (IL-25, IL-33, and TSLP) and Th2-related loci are prominent." (PMID 40806756, 2025). "Recent studies have demonstrated that damaged airway epithelium plays a critical role in mediating inflammation-driven indirect AHR in asthma through the release of cytokines such as thymic stromal lymphopoietin and IL33." (PMID 40598285, 2025). "IL-33 involvement in asthma progression has the potential for discovering a new treatment involving inhibiting its secretion and analyzing the treatments known to medicine today." (PMID 40723867, 2025). "This is in line with our observation of significant increases in TSLP, IL-33, and IL-25 protein levels following T2 stimulation and viral infection, specifically in asthma-derived BECs." (PMID 40370530, 2025). "Recent studies have shown that IL-33 plays a central role in promoting Th2 airway inflammation by activating type 2 immunity in asthma patients." (PMID 40546642, 2025). "Currently, data from two Phase II clinical trials have shown that targeting IL-33 monoclonal antibodies or IL-33R monoclonal antibodies reduces acute asthma attacks compared to placebo." (PMID 39806440, 2025). "Several monoclonal antibodies targeting IL-33 have been developed, primarily for conditions such as chronic obstructive pulmonary disease and asthma." (PMID 40764944, 2025). "Itepekimab is an anti-IL-33 biologic studied in combination with dupilumab in a phase 2 trial over 12 weeks for asthma control." (PMID 40863432, 2025). "In a mouse model of ovalbumin-induced asthma, administration of anti-IL-33 antibodies was shown to decrease eosinophil infiltration, IgE production, and Th2 cytokine release, as well as airway hyperreactivity (AHR)." (PMID 41409758, 2025).
asthma (continued). "Instead, a potential involvement of the TSLP and IL-33 in asthma vascular remodeling emerged from interesting findings in the correlation analyses." (PMID 40022191, 2025). "For example, in asthma, the AS of IL-33 results in the generation of isoforms that drive inflammation." (PMID 40563429, 2025). "IL-33 and Th17 cytokines have been mechanistically linked to TET1-mediated promoter demethylation in asthma models." (PMID 41020825, 2025). "Promising results have also been obtained with IL-33 blockade, and given the success in asthma, the results with tezepelumab in COPD patients are awaited." (PMID 41145900, 2025). "Interleukin-33 (IL-33), an epithelial-derived alarmin upregulated in asthma, directly inhibits GPX4 expression—simultaneously exacerbating ferroptosis and promoting type 2 inflammation." (PMID 41573584, 2025). "It is known that epithelial cells and innate lymphoid cells in airways of patients with asthma have an enhanced production of IL-13, IL-25, and IL-33 and a deficit in type I and III interferon responses that are needed for effective antiviral clearance." (PMID 39507925, 2025). "IL-33 is expressed in human lung airway epithelial basal cells, endothelial cells, and fibroblasts, which reflects the possible pathogenic role of IL-33 and ST2 in asthma." (PMID 39925809, 2025). "IL-33 can increase IgE-induced inflammation and the level of IL-33 is elevated in patients with acute allergic diseases such as asthma and atopic dermatitis." (PMID 38755659, 2024). "Tozorakimab (MEDI3506), developed by AstraZeneca, is an anti-IL-33 antibody currently being investigated for its efficacy in treating asthma." (PMID 39457624, 2024). "This points to the role of IL-33 as an alarmin and highlights the importance of the SNP we also investigated in the pathogenesis of asthma." (PMID 38731070, 2024). "Among these, TSLP, IL-25, and IL-33 play pivotal roles as upstream regulators, initiating and amplifying inflammatory pathways that drive asthma symptoms, making them critical targets for therapeutic interventions." (PMID 39457624, 2024). "The IL33/IL1RL1 axis represents a therapeutic opportunity for asthma and allergic diseases and is of interest for several pharmaceutical companies developing selective inhibitors/blocking antibodies." (PMID 39301832, 2024). "Histological observations suggested that IL-33 release into the airway lumen increases with asthma severity." (PMID 38731070, 2024). "Coincidentally, Yang indicated that OS alleviates ovalbumin-induced lung inflammation by restraining IL-33/ST2 signaling in a mouse model of asthma." (PMID 39334402, 2024). "The model gastrointestinal nematode Heligmosomoides polygyrus bakeri secretes the Alarmin Release Inhibitor HpARI2, an effector protein that suppresses protective immune responses and asthma in its host by inhibiting IL-33 signalling." (PMID 38890291, 2024). "In patients with severe asthma, the number of peripheral eosinophils producing EETs is elevated, and these cells stimulate lung epithelial cells to generate IL-33 and TSLP." (PMID 39060923, 2024). "Exposure to inhaled asthma triggers causes the release of epithelial cytokines (TSLP, IL-25 and IL-33), which promotes both innate and adaptive T2 immune responses." (PMID 38453256, 2024). "Investigations have shown that the ablation of this gene in murine models of asthma, which are induced by IL-33, leads to impaired mitochondrial function." (PMID 39382744, 2024). "Anti‐IL‐33 antibodies have been tested as therapies for pulmonary diseases including asthma and COPD as a Phase II trial." (PMID 39654685, 2024). "In a study of children with asthma, the proportions of Th2 cells, eosinophils, and mast cells and the level of IL-33 in the serum were significantly increased, and there was a positive correlation with the level of the autoantibody IgE in the body." (PMID 39719880, 2024).
asthma (continued). "Studies conducted in children with asthma show similar observations; furthermore, they indicate a correlation between serum IL-33 levels and the severity of the disease—the more severe the symptoms of asthma, the higher the concentration of IL-33." (PMID 38731070, 2024). "Elevation of the expression of IL‐33 has been shown in a large number of allergic disorders, including asthma, chronic rhinosinusitis, allergic rhinitis, atopic dermatitis and eosinophilic esophagitis." (PMID 39654685, 2024). "Upstream epithelial cytokines, collectively termed alarmins (such as thymic stromal lymphopoietin (TSLP) and IL-33), have been established as key drivers of asthma pathobiology from the top of the immunologic cascade." (PMID 39694589, 2024). "This study investigated the relationship between serum IL-33 and TSLP levels and asthma, along with polymorphisms in the IL-33 and TSLP genes and asthma susceptibility." (PMID 38731070, 2024). "These structures can disturb the integrity of bronchial epithelial cells, leading to the release of cytokines such as TSLP and IL-33, which can exacerbate the pathology of asthma." (PMID 39060923, 2024). "A CpG-oligodeoxynucleotide alleviates Th2/Th17 inflammatory response, airway inflammation and remodeling in mice with smoke-related asthma by downregulating the IL-33/ST2 axis." (PMID 38650035, 2024). "In doing so, HpARI2 effectively blocks IL-33 responses in acute and chronic models of asthma and when administered in models of other nematode infections." (PMID 38890291, 2024). "The findings demonstrated the critical roles that TSLP and IL-33 play in the aetiology of asthma, which is typified by enduring airway inflammation and reduced lung function, indicating their potential as molecular targets." (PMID 39057040, 2024). "In this study, an increased production of IL-33 and TSLP was associated with increased asthma severity, whereas increased production of pro-inflammatory cytokines was linked to decreased production of IFN-β." (PMID 39694589, 2024). "The researchers measured IL-33 levels in the serum of 44 children with intermittent/mild asthma and 26 healthy controls aged 5–15." (PMID 38731070, 2024). "The development of anti-IL-33 monoclonal antibodies has also shown some promise in asthma clinical trials." (PMID 39457624, 2024). "TSLP, IL-25, and IL-33 are regarded as primary molecules involved in type 2 inflammatory response and have a crucial role in the pathogenesis of asthma." (PMID 39060923, 2024). "Functions of IL-33 are very well documented in the lungs during asthma while systemic functions during allergic inflammation are not well described and are sometimes divergent." (PMID 39244793, 2024). "In summary, IL-33, a cytokine of the interleukin family, has emerged as a critical player in respiratory type 2 inflammation and is pivotal in the development of asthma, allergic rhinitis, and various other respiratory diseases." (PMID 39301028, 2024). "This brings about the activation of pro-oxidant enzymes, such as DUOX1, and increases IL33 production and, ultimately, airway epithelial injury, predisposing PCD lungs toward asthma development." (PMID 39337527, 2024). "Encouragingly, the potential clinical benefit of IL-33 blockade has been indicated by phase 2 clinical studies in patients with moderate-to-severe asthma and in former smokers with chronic obstructive pulmonary disease." (PMID 38899206, 2024). "For instance, blockade of IL-33 using therapeutic antibodies has shown encouraging efficacy in clinical trials of asthma and chronic obstructive pulmonary disease." (PMID 38172258, 2024). "Increasing evidence indicates that biological therapies targeting IgE, IL-5/IL-5Rα, TSLP and IL-33/ST2 can improve not only clinical symptoms but also certain features of airway remodelling in asthma." (PMID 38609094, 2024).